PALM2AKAP2 (PALM2 and AKAP2 fusion)
Description:
Binds to regulatory subunit (RII) of protein kinase A. May be involved in establishing polarity in signaling systems or in integrating PKA-RII isoforms with downstream effectors to capture, amplify and focus diffuse, trans-cellular signals carried by cAMP. Binds to and modulates the structure of the actin cytoskeleton.
Synonyms: PRKA2; PALM2; AKAP-KL; AKAP2; AKAPKL; MISP2; PALM2-AKAP2
Tractability: Antibody: UniProt places it where antibodies can reach, with medium confidence; its Gene Ontology location is reachable by antibodies, with medium confidence; the Human Protein Atlas places it where antibodies can reach. PROTAC: UniProt records ubiquitination sites on it; ubiquitination databases record sites on it.
Gene: Protein-coding gene on chromosome 9 (109,498,325 to 110,172,512, forward strand). Ensembl gene ENSG00000157654.
Subcellular location: Apical cell membrane
Subcellular location (Human Protein Atlas): Plasma membrane
Gene Ontology:
Molecular function: protein binding
Biological process: regulation of cell shape
Cellular component: plasma membrane; apical plasma membrane; membrane
Genetic constraint (gnomAD): Loss-of-function variants: 37 observed, 71.27 expected, observed/expected ratio (o/e) 0.52, 90% interval 0.4 to 0.68. The upper end of that interval is the gene's LOEUF score, 0.68, which puts it in group 2 of 6, group 1 being the genes least tolerant of losing a copy. Missense variants: 1,224 observed, 1,227.7 expected, observed/expected ratio (o/e) 1, 90% interval 0.95 to 1.04. Synonymous variants: 468 observed, 494.97 expected, observed/expected ratio (o/e) 0.95, 90% interval 0.88 to 1.02.
Homologues: Orthologues: macaque PALM2AKAP2 (96% identical), chimpanzee PALM2AKAP2 (83% identical), pig PALM2AKAP2 (83% identical), rat Pakap (81% identical), guinea pig PALM2AKAP2 (72% identical), mouse Pakap (67% identical), tropical clawed frog palm2akap2 (51% identical). Paralogues in human: PALM3 (10% identical), PALMD (8% identical), PALM (7% identical).
Diseases named in the same sentence as PALM2AKAP2 in open-access papers:
PALM2AKAP2 is named in the same sentence as 24 diseases in open-access papers, as found by Europe PMC text mining. Sharing a sentence is not in itself a finding about the gene and the disease. The quoted sentences say what the papers report.
colorectal cancer (1 paper, 2023). A primary or metastatic malignant neoplasm that affects the colon or rectum. "PALM2-AKAP2 is a newly named fusion gene with a yet unknown function, but it has been correlated with functions similar to the previously distinct PALM2 and AKAP2 genes, such as proliferation in colorectal cancer cell lines." (PMID 37621654, 2023).
PALM2AKAP2 also shares sentences with these, for which no sentence is quoted: cancer (6 papers); tumor (3); adolescent idiopathic scoliosis (2); myocardial infarction (2); ovarian carcinoma (2); CAEBV infection (1); cardiac hypertrophy (1); chronic gastritis (1); esophageal cancer (1); esophageal squamous cell carcinoma (1); frontotemporal dementia (1); gastric cancer (1); Graves disease (1); idiopathic scoliosis (1); melanoma (1); metastatic cancer (1); metastatic prostate carcinoma (1); NK/T-cell lymphoma (1); non-small cell lung carcinoma (1); osteoporosis (1); prostate carcinoma (1); psychiatric disorder (1); systemic lupus erythematosus (1).